UHRF1 (ubiquitin like with PHD and ring finger domains 1)
Diseases named in the same sentence as UHRF1 in open-access papers (continued):
Sharing a sentence is not in itself a finding about the gene and the disease.
liver cancer (12 papers, 2016 to 2024). An epithelial or non-epithelial malignant neoplasm that arises from the liver. "UHRF1 is often over-expressed in human liver cancer and high UHRF1 levels are associated with a poor prognosis." (PMID 33732709, 2021). "In conclusion, our in silico analysis revealed a high concomitant expression of the epigenetic genes DNMT1, EHMT2, and UHRF1 in liver cancer patients with inferior outcomes." (PMID 38285887, 2024). "Our findings provide mechanistic insights and identify UHRF1 as a potential target for liver cancer therapies." (PMID 37380646, 2023). "Compared with normal liver tissues, the expression of UHRF1 in liver cancer was upregulated by 17.73-fold." (PMID 34249673, 2021). "In the same study, UHRF1 is identified as involved in the upstream regulation of MEG3 in liver cancer by regulating DNMT1." (PMID 31341758, 2019). "Repression of SP1 activity by T3 receptor pathway activation downregulates UHRF1, relieves p21 from UHRF1-mediated silencing and induces cell cycle arrest at G0/G1 phase in liver cancer cells." (PMID 28881702, 2017). "UHRF1 was shown to be overexpressed in liver cancer patients and its overexpression was accompanied with the size of tumor." (PMID 27839516, 2016). "Taken together, these findings show that T3/TRα1 pathway is involved in the regulation of UHRF1 expression in liver cancer through the transcription factor Sp1." (PMID 27839516, 2016). "Interestingly, UHRF1 over-expression was shown to induce hypomethylation in human liver cancer, as observed upon its depletion in mouse, where it induced epigenetic compensation." (PMID 33732709, 2021). "Next, we wanted to evaluate the survival probability of liver cancer patients with high-expression and low-expression of DNMT1, EHMT2, and UHRF1 genes." (PMID 38285887, 2024). "In liver cancer tissues, MEG3 is negatively correlated with UHRF1 that plays an important role in DNA methylation by recruiting DNA methyltransferase DNMT1 during DNA replication." (PMID 31341758, 2019).
melanoma (10 papers, 2013 to 2025). A malignant, usually aggressive tumor composed of atypical, neoplastic melanocytes. "In melanoma, a higher expression of UHRF1 is positively linked with the proliferation marker Ki67, highlighting UHRF1’s role in facilitating melanoma cell division and tumor expansion." (PMID 39051184, 2024). "As reported, UHRF1-mediated ubiquitination regulates EZH2 proteins to induce differentiation phenotypes in melanoma." (PMID 39709438, 2024). "IHC staining of UHRF1 expression in human melanomas showed that highly pigmented cells exhibiting increased UBE2L6 and decreased EZH2 also had low UHRF1 expression." (PMID 36906655, 2023). "Similarly, DEPDC1B SHCBP1, RRM2, PLK1, and UHRF1 have been found to promote melanoma proliferation and could be potential targets for treatment; their coefficients were all positive, which implies that they had an additive effect on the risk scores." (PMID 34384498, 2021). "In agreement with this hypothesis, we have recently shown that curcumin inhibited melanoma cell proliferation and cell cycle progression by accumulating cells at the G2/M-phase with decreased expression of UHRF1 and DNMT1 and enhanced expression of p21, a p16INK4A -homolog." (PMID 23688286, 2013). "To understand UBE2L6 methylation, we focused on the RING E3 ubiquitin ligase UHRF1, previously shown to downregulate UBE2L6 and promote melanoma cell proliferation." (PMID 36906655, 2023). "Curcumin was found to decrease the expressions of PDE1A, cyclin A, UHRF1, and DNMT1 in melanoma cells." (PMID 29899856, 2018). "Anti-proliferative effect of curcumin on melanoma cells has been documented by direct inhibition of PDE1, a regulator of UHRF1." (PMID 29899856, 2018). "Our studies extend understanding of this oncoprotein by demonstrating UHRF1/UBE2L6/UBR4-mediated EZH2 promotion to enhance LPC phenotypes and disease progression in melanoma, providing a mechanism as to how higher levels of EZH2 are associated with late-stage disease." (PMID 36906655, 2023).
acute lymphoblastic leukemia (9 papers, 2012 to 2025). Leukemia with an acute onset, characterized by the presence of lymphoblasts in the bone marrow and the peripheral blood. "In vitro and in vivo Acute Lymphoblastic Leukemia (ALL) models reveal that MIF is positively regulated by UHRF1 (ICBP90) and negatively regulated by HBP1, both of which drive MIF overexpression in disease progression by binding to the promotor region." (PMID 38732068, 2024). "UHRF1 regulates and maintains the levels of ROR1 and is required for the viability of lymphoblastic leukemia through a mechanism associated with ROR1 expression." (PMID 37630248, 2023). "Several investigations showed that TQ could induce apoptosis and cell cycle arrest in lymphoblastic leukemia Jurkat cells via the down-regulation of UHRF1 (an oncogenic factor and silenced of tumor suppressor genes)." (PMID 34835969, 2021). "Specifically, thymoquinone suppresses PDE1A expression and inhibits UHRF1 via a p73-dependent mechanism, suggesting potential application in acute lymphoblastic leukemia (ALL) therapy." (PMID 41179677, 2025). "The inhibition of UHRF1 in combination with desatinib leads to a decrease in the ROR1 levels, suggesting a novel mechanism to target acute lymphoblastic leukemia." (PMID 37630248, 2023).
glioma (9 papers, 2010 to 2024). A benign or malignant brain and spinal cord tumor that arises from glial cells (astrocytes, oligodendrocytes, ependymal cells). "Collectively, all our data identified the disruption of the Dnmt1/PCNA/UHRF1 interactions as a molecular event associated with the degree of global DNA hypomethylation in glial/glioma cells." (PMID 20613874, 2010). "In the present article, we report that Akt overexpression and diuron exposure promote the glioma formation from neural progenitor cells via the induction of DNA hypomethylation mediated by two distinct pathways: the loss of DNMT1/PCNA/UHRF1 interactions and the APOBEC3γ overexpression." (PMID 31727122, 2019). "To further corroborate these findings, we also examined c-Myc and UHRF1 expression in histological sections obtained from WHO grade IV gliomas and normal brain tissue samples." (PMID 38246990, 2024). "The results showed significant differences (p < 0.05) in the level of UHRF1 gene expression between both types of tested glioma cells." (PMID 30171426, 2018). "Here, we show that the disruption of Dnmt1/PCNA/UHRF1 interactions promotes a global DNA hypomethylation in human gliomas." (PMID 20613874, 2010). "We then demonstrate that the Dnmt1 phosphorylations by Akt and/or PKC abrogate the interactions of Dnmt1 with PCNA and UHRF1 in cellular and acelluar studies including mass spectrometric analyses and the use of primary cultured patient-derived glioma." (PMID 20613874, 2010). "Both c-Myc and UHRF1 were increased in high-grade gliomas compared to normal brain tissue." (PMID 38246990, 2024). "While c-Myc has been well-characterized as an oncogene, the function of UHRF1 in human glioma remains unclear." (PMID 38246990, 2024). "The transcriptional co-repressor function of UHRF1 was illustrated in experiments conducted on glioma and mesothelioma cells, in which UHRF1 contributed to the epigenetic silencing of NY-ESO1, a cancer-testis antigen regarded as a target for cancer immunotherapy." (PMID 39519018, 2024). "Thus, we conclude that the loss of DNMT1/UHRF1/PCNA and the APOBEC3γ overexpression are the two leading molecular causes of the global DNA hypomethylation seen in cells at the origin of Akt + diuron-induced glioma." (PMID 31727122, 2019). "In addition, to determine whether Rc TR extract could induce the apoptosis of glioma cells, we evaluated the levels of DNA epigenetic markers such as UHRF1 and DNMT1." (PMID 30171426, 2018). "In addition, to determine whether Rc TR extract could induce the apoptosis of glioma cells, the levels of two DNA epigenetic markers, UHRF1 and DNMT1, were evaluated." (PMID 30171426, 2018). "Both plant extracts (with IC50 concentration for grade IV glioma cells and U87MG cells) showed down-regulation of UHRF1 and DNMT1 gene expression after treatment with TR and AtPAP1 root extracts on both tested lines." (PMID 29786770, 2018). "The mRNA levels of UHRF1 and DNMT1 were found to be reduced in both glioma cell lines treated with Rc TR extract." (PMID 30171426, 2018). "Our findings indicate that the mRNA levels of UHRF1 and DNMT1 were reduced in glioma cell lines treated with Rhaponticum carthamoides TR extract." (PMID 30171426, 2018). "S127 and S143 phosphorylations mediated by PKC (protein kinase C) and AKT (also called PKB, protein kinase B) were observed in glioma and provoked the disruption of DNMT1/PCNA/UHRF1 complex and a consecutive global DNA hypomethylation." (PMID 29449903, 2018). "Finally, we examined the levels of c-Myc and UHRF1 protein in NHA, the three glioma cell lines (A172, LN229, and U251) and in P3, BG5, and BG7 human GSCs." (PMID 38246990, 2024).
glioma (continued). "Moreover, both c-Myc and UHRF1 were highly expressed in GSCs, low in glioma cell lines, and no expression in the NHA." (PMID 38246990, 2024).
lung adenocarcinoma (9 papers, 2016 to 2024). A carcinoma that arises from the lung and is characterized by the presence of malignant glandular epithelial cells. "Among these genes, UHRF1, which has been demonstrated experimentally can promote disease progression and is associated with poor prognosis by affecting the cell cycle pathway in lung adenocarcinoma, which is consistent with our findings." (PMID 33714206, 2021). "Furthermore, the inferred activity of FOXA2, FOXM1, and UHRF1 were significantly associated with survival in several lung adenocarcinoma cohorts." (PMID 31503425, 2019). "Recent studies suggest that UHRF1 knockdown can affect the lung adenocarcinoma (ADC) cell cycle and induce apoptosis, and the results show that UHRF1 upregulation can promote the survival of ADC cells by triggering the cell cycle pathway." (PMID 35656341, 2022). "UHRF1 expression was also significantly higher in lung adenocarcinoma tissues in the Selamat lung dataset (fold change=3.105; P=1.19E-20) and Okayama lung dataset (fold change=2.81; P=5.94E-11), respectively." (PMID 33658396, 2021). "UHRF1 expression was significantly higher in lung adenocarcinoma (fold change=5.119, P=1.15E-18), squamous cell lung carcinoma (fold change=7.661; P=5.81E-23), and large cell lung carcinoma (fold change=8.517; P=2.04E-08) tissues in the Hou lung dataset." (PMID 33658396, 2021). "Surprisingly, the up‐regulated UHRF1 is only associated with the overall survival of lung adenocarcinoma (ADC) and knockdown of UHRF1 dramatically attenuates ADC tumorigenesis." (PMID 32495469, 2020). "On the other hand, FOXM1 and UHRF1 were activated in lung adenocarcinoma, with increased expression of their positive targets and/or decreased expression of their negative targets." (PMID 31503425, 2019). "However, UHRF1 was also a proto-oncogene that overexpressed in several tumor tissues and high UHRF1 expression is a marker of poor prognosis in human KRAS mutant lung adenocarcinoma, while the exact role of UHRF1 in tumorigenesis remains elusive." (PMID 39341501, 2024). "Thus, we performed survival analysis using the lung adenocarcinoma (LUAD) tumor dataset from the cancer genome atlas (TCGA) stratified by UHRF1 expression (high vs normal)." (PMID 37407562, 2023). "The Cancer Genome Atlas (TCGA) data suggest UHRF1 is significantly overexpressed in malignancies that frequently present RB pathway inactivation including sarcomas, breast invasive carcinomas, and lung adenocarcinomas, but not in cancers where RB1 loss is infrequent, like prostate adenocarcinomas." (PMID 36068209, 2022). "Analysis of UHRF1 RNA and protein expression in human NSCLC cell lines and patient lung adenocarcinoma samples from TCGA demonstrated a tendency towards higher UHRF1 expression in KRAS mutant cell lines." (PMID 37407562, 2023). "It is also overexpressed at the mRNA levels in lung adenocarcinomas and squamous cell carcinomas compared to normal tissue, although not as highly as UHRF1 or DNMTs." (PMID 27738314, 2016).
colitis (7 papers, 2020 to 2025). Inflammation of the colon. "In contrast, other studies demonstrate that iTregs generated from UHRF1-deficient CD4+ T cells exhibit hypersuppressive function when adoptively transferred into lymphocyte-deficient mice with Tconv cell–mediated colitis." (PMID 40956625, 2025). "In mice, knockout of Uhrf1 decreases mCG at the Tnf promoter and increases the expression of Tnf in macrophages, which causes colitis, a type of inflammatory bowel disease (IBD)." (PMID 35646933, 2022). "T cell-specific deletion of Uhrf1 will affect the expression of normal cell cycle genes in Treg cells, leading to spontaneous colitis." (PMID 39200098, 2024). "Uhrf1-mediated tnf-α gene methylation controlled proinflammatory macrophages in experimental colitis resembling inflammatory bowel disease." (PMID 34858994, 2021). "Mice with macrophages deficient for UHRF1 manifest with TNF-α overexpression and aggravated DSS-induced colitis." (PMID 32848509, 2020). "Published data suggest that UHRF1 is dispensable for iTreg generation, yet others have reported that iTreg generation from UHRF1-deficient CD4+ Tconv cells augments their suppressive function in a colitis model of inflammation." (PMID 40956625, 2025). "Moreover, the intestinal microbiota regulates the DNA methylation of Treg cells via promoting Uhrf1 expression, thereby modulating the occurrence of spontaneous colitis." (PMID 39200098, 2024). "Also, the loss of function in UHRF1 reduces the methylation of the TNF-α promoter in macrophages, indicating the regulatory role of UHRF1 in the mouse model of colitis." (PMID 32848509, 2020). "However, UHRF1 may effect differently among subtypes of regulatory T (Treg) cells, as UHRF1 maintains the proliferation and maturation of colonic Treg cells but inhibits the differentiation of peripheral induced Treg cells in the development of colitis." (PMID 32848509, 2020).
lymphoma (7 papers, 2018 to 2025). A malignant (clonal) proliferation of B- lymphocytes or T- lymphocytes which involves the lymph nodes, bone marrow and/or extranodal sites. "High mRNA expression levels of UHRF1 were most pronounced in B-lymphoblastic leukemia/lymphoma cell lines." (PMID 40301374, 2025). "Emodin was found to downregulate UHRF1, and therefore lead to a decrease in the lymphoma Raji cell viability, induction of apoptosis, and increased the activation of caspase-3, caspase-9 and poly (ADP-ribose) polymerase." (PMID 29899856, 2018). "Our data revealed that N3a-treatment may directly lead to increase in the master epigenetic conductor UHRF1 and its privileged partner DNMT1, over-expressed in different cancer types and lymphomas, promoting cell growth inhibition." (PMID 37568720, 2023). "Combined depletion of UHRF1 and PCLAF might thus co-operate to the anti-tumorigenic effects of HDACi in lymphoma treatment." (PMID 32264925, 2020).
non-small cell lung carcinoma (7 papers, 2010 to 2025). A group of at least three distinct histological types of lung cancer, including non-small cell squamous cell carcinoma, adenocarcinoma, and large cell carcinoma. "As the recent reports have shown, long non-coding RNA UPAT promotes cell proliferation via increasing UHRF1 expression in non-small cell lung cancer." (PMID 31399501, 2019). "Using a combination of genetically engineered mouse models, loss-of-function RNAi screens in primary tumor cells derived from these models, and 3D cultures of human non-small cell lung cancer cell lines we show that UHRF1 plays a key role in KRAS-driven oncogenesis." (PMID 37407562, 2023). "UHRF1 interacts with WDR79 in Non-Small Cell Lung Cancer (NSCLC), and the knockdown of WDR79 promotes the ubiquitination levels of UHRF1 protein." (PMID 38725075, 2024).
hepatoblastoma (6 papers, 2018 to 2024). Hepatoblastoma (HB) is a malignant hepatic tumor and is the most common pediatric liver cancer. "In the context of hepatoblastoma, the enrichment of 5-hydroxymethylcytosine has been associated with disrupted expression of UHRF1, TET1, and TET2." (PMID 39595571, 2024). "During hepatoblastoma, a general disruption in the expression of genes from the epigenetic machinery was observed, mainly upregulation of UHRF1, TET1, and TET2, in association with an enrichment of 5 hmC content." (PMID 39684755, 2024). "We observed in hepatoblastomas a general disrupted expression of these genes from the epigenetic machinery, mainly UHRF1, TET1, and TET2 upregulation, in association with an enrichment of 5hmC content." (PMID 31249594, 2019). "These alterations support a model of active demethylation by TETs in hepatoblastoma, probably during early stages of liver development, which, in combination with UHRF1 overexpression, would lead to DNA hypomethylation and an increase in overall 5 hmC content." (PMID 39684755, 2024). "The UHRF1/HAUSP/DNMT1 complex was also detected on the promoters of HHIP and IGFBP3, two key TSGs in hepatoblastoma, and this interaction caused the inhibition of these genes." (PMID 33922029, 2021). "Our findings support a model of active demethylation by TETs in hepatoblastoma, probably during early stages of liver development, which in combination with UHRF1 overexpression would lead to DNA hypomethylation and an increase in overall 5hmC content." (PMID 31249594, 2019). "It is known that UHRF1/DNMT1 are involved in the maintenance of the hypermethylation of tumor suppressor gene promoters in cancer; in particular, overexpression of UHRF1 was recently reported to silence specific tumor suppressor genes in hepatoblastomas." (PMID 31249594, 2019). "Employing chromatin immunoprecipitations (CHIP), one study has suggested that E3 ubiquitin-like containing PHD and RING finger domain 1 (UHRF1) may play a crucial role in the profound silencing of tumor suppressor genes (TSGs) such as HHIP, IGFBP3, and SFRP1 in hepatoblastoma." (PMID 38390281, 2024). "Interestingly, the depletion of UHRF1, but not of its partner HAUSP, significantly increased the expression of the HHIP and IGFBP3 genes and decreased the H3K9me2 mark at the HHIP and IGFBP3 TSG loci, leading to the inhibition of hepatoblastoma cell growth." (PMID 33922029, 2021).